IL6 (interleukin 6)
Diseases named in the same sentence as IL6 in open-access papers (continued):
Sharing a sentence is not in itself a finding about the gene and the disease.
periodontitis (continued). "Patients with these syndromes are reported to exhibit upregulated IL6 and a higher risk of periodontitis." (PMID 38396821, 2024). "Among the interleukins released during inflammatory processes, IL-6, IL-8, and IL-1β have been widely explored in periodontal medicine for their possible joint pathogenic involvement in periodontitis and other systemic inflammatory conditions." (PMID 38877442, 2024). "This study focused on measuring the pro-inflammatory cytokines TNF-α, IL-1β, IL-6, and IL-8, pivotal not only in periodontitis but also in cancer-associated chronic inflammation." (PMID 38612423, 2024). "Periodontitis is an inflammatory disease, and inflammatory factors such as IL-1, IL-6 and TNF-α are directly associated with periodontitis." (PMID 39124790, 2024). "Previous studies have shown an association of IL-6 gene polymorphisms with the development of periodontitis." (PMID 39458264, 2024). "This study aimed to evaluate the association of the IL-6 receptor gene rs1800795 polymorphism with the risk of periodontitis and selected clinical parameters, as well as to assess the expression of IL-6 in gingival tissue in patients with periodontitis." (PMID 39458264, 2024). "IL-6, a pro-inflammatory cytokine, is implicated in bone destruction during infection and has been found to be elevated in patients with periodontitis compared to healthy individuals." (PMID 39125970, 2024). "Previous investigations have revealed that CRP plays a vital role in the development of periodontitis, a significant cause of tooth loss, by causing the production of inflammatory mediators, such as IL-1, IL-6, and TNF-α." (PMID 38066835, 2023). "In this study, we tested the biological effect of IL-6 signaling downregulation on the risk of periodontitis simulating the effect of monoclonal antibodies that target IL-6R by blocking both IL-6 classic and trans-signaling." (PMID 37342352, 2023). "Severely high- glucose (50 mM) concentrations decreased the proliferation and migration activity of PDLFs, increased cellular cytotoxicity, and induced the expression of IL-6 and IL-23 inflammatory mediators associated with periodontitis." (PMID 37189437, 2023). "In this study, we assessed the potential benefit of inhibiting IL-6 signaling to reduce the risk of periodontitis using the principle of instrumental variable estimation." (PMID 37342352, 2023). "For example, a meta-analysis has included 21 case-control studies to explore the association between IL6 polymorphism and periodontitis susceptibility." (PMID 36793899, 2023). "Cytokines that are frequently associated with periodontitis are IL-1β, IL-6, IL-12, IL-16, IL-17, IL-21, and TNF-α." (PMID 37106750, 2023). "Instead, CRP is a direct indicator of IL-6 signaling, and according to our analysis a possible causal mediator for the risk of periodontitis." (PMID 37342352, 2023). "Previous reports have demonstrated that, a proportional increase of salivary IL-6 was associated with a significant trend of periodontitis." (PMID 37365568, 2023). "Both epistatic genes had the smallest biofilm lysine content of their respective GCF response groups, which correlates with a report of IL6-1363(T) being associated with aggressive (severe) periodontitis." (PMID 37762554, 2023). "In conclusion, we found genetic evidence for a reduced risk of periodontitis through downregulation of IL-6 signaling." (PMID 37342352, 2023). "Violin plots showing expression levels of the genes encoding interleukin (IL)-6 (Il6) (A) and IL-23 (Il23a) (B) in each major cell type, fibroblast subpopulations, and myeloid cell subpopulations during periodontitis development." (PMID 38015204, 2023). "When tested in Sprague–Dawley rats with ligation-induced periodontitis, carvacrol treatment decreased alveolar bone loss and the relative mRNA expression of inflammatory indicators such as Tnfa, Il1b, Il6, and Nos2." (PMID 37894657, 2023).
periodontitis (continued). "More specifically, proinflammatory cytokines such as TNF-α, IL-1, and IL-6 have been implicated in the activation of osteoclastic bone resorption in periodontitis." (PMID 37214190, 2023). "Regarding the IL-6 -572 C/G gene polymorphism, the percentage of the GG genotype was higher in the moderate–severe periodontitis group (10%) than in the mild periodontitis group (2.5%)." (PMID 37239434, 2023). "Genetically proxied downregulation of IL-6 signaling was associated with lower odds of periodontitis (odds ratio (OR) = 0.81 per 1-unit decrement in log-CRP levels; 95% confidence interval (CI): [0.66;0.99]; P = 0.0497)." (PMID 37342352, 2023). "The statistical analysis shows that IL-6 and nitric oxide were the biomarkers that showed the greatest value of significant association with periodontitis (P < 0.00001), accompanied by IL-1B (P < 0.0001), TNF-α (P = 0.004) and osteoprotegerin (P = 0.01)." (PMID 37026605, 2023). "Another promoting influence for chronic inflammatory diseases such as periodontitis and peri-implantitis is associated with increased IL-6 expression." (PMID 35819566, 2022). "Activation of the inflammatory response in plaque-stimulated periodontal tissues is the underlying pathological change in chronic periodontitis, and periodontal tissues release large amounts of inflammatory factors such as IL-1β, IL-6, IL-17, and TNF-α." (PMID 35942384, 2022). "For example, HGFs produce proinflammatory cytokines, interleukin-6 (IL-6) and interleukin-8 (IL-8), which are closely linked to periodontitis and are associated with periodontal tissue destruction and alveolar bone loss." (PMID 36071855, 2022). "Activated macrophages and lymphocytes produce IL-1β, which is necessary for T cell activation and proliferation, and cooperate with IL-6 to cause periodontal tissue damage and promote periodontitis." (PMID 36710972, 2022). "We evaluated the expression levels of known proinflammatory cytokines associated with periodontitis (IL-1β, IL-6, and TNF-α)." (PMID 36319994, 2022). "This was also associated with a reduction of reduced serum IL-6, TNFα, and IL-1β in patients with periodontitis compared to baseline." (PMID 35874771, 2022). "G/G genotype of IL-6 rs1800796 was associated with an increased risk of chronic periodontitis in a meta-analysis." (PMID 35454140, 2022). "Among the primary proinflammatory cytokines associated with periodontitis, interleukin (IL)-6 promotes the cascade of destructive tissue processes." (PMID 35628348, 2022). "In contrast, in patients with calcified dental plaque composed of calcium phosphate mineral salts and surrounded by a non-mineralized bacterial layer (called dental calculus), the salivary IL-6 concentration was higher with associated chronic periodontitis." (PMID 35054284, 2022). "The present study also revealed that periodontitis is associated with increased IL-6 and CXCL2 levels in human and rat gingiva." (PMID 34024010, 2022). "In the Brazilian population, on the other hand, the GG genotype for polymorphism in the IL-6-174 locus was much more common in patients with periodontitis than in healthy subjects, and its incidence increased with the severity of the disease." (PMID 35454140, 2022). "Elevated IL-6 levels are associated with periodontal tissue degradation, chronic apical periodontitis, and early childhood caries." (PMID 36358132, 2022). "There are several polymorphisms in the promoter region of IL-6, and among them the IL-6 174 GG genotype plays as a risk factor of chronic periodontitis in Brazilian and Caucasian population." (PMID 36127718, 2022). "IL-6 and IL-1β are pro-inflammatory cytokines that are associated with chronic inflammation, periodontitis, and osteoclast bone resorption." (PMID 35628390, 2022). "The gene expression analyses of the gingiva of rats with experimental periodontitis and/or orthodontic tooth movement also showed that periodontal inflammation was associated with an increase in IL-6 and CXCL2 levels at 8 day." (PMID 34024010, 2022).
periodontitis (continued). "During the inflammatory response, IL-6 is one of the main host inflammatory mediators involved and along with other inflammatory mediators implicated, it prevents the progression of periodontitis and periodontal tissue destruction." (PMID 34790237, 2021). "Unlike homeostatic oral Th17 cell accumulation, in a commensal-independent and IL-6-dependent manner, periodontitis-associated expansion of Th17 cells was dependent upon the local dysbiotic microbiome and required both IL-6 and IL-23." (PMID 33763040, 2021). "The question of this study is as follows: in aging adults, do chronic apical periodontitis lesions as biomarkers have a risk effect on the immunoexpression of pro-inflammatory cytokines (IL-1β, IL-6 and TNF-α) compared to adults?" (PMID 35053012, 2021). "IL-6 −174G/C G allele model had a weak relationship in the prevention of periodontitis risk with OR (95% CI), 1.10 (0.82–1.38)." (PMID 35046930, 2021). "It has been demonstrated that periodontal patients presented higher salivary IL-6 than healthy subjects and also a proportional increase of salivary IL-6 were associated with the extent of periodontitis and tooth loss." (PMID 34790237, 2021). "Cytokines and other molecules can be used to diagnose periodontitis, in which the combination of IL-6 and MMP-8 shows the best diagnostic performance." (PMID 34868054, 2021). "IL-23, together with IL-6, is involved in the differentiation of pathogenic Th17 cells during periodontitis." (PMID 33562334, 2021). "Emerging experimental and clinical studies have demonstrated that TNF-α, IL-1β, and IL-6 are associated with the initiation and progression of periodontitis." (PMID 34395635, 2021). "Periodontitis is the cause of a systemic inflammatory process mediated by C-reactive protein, interleukin 1b (IL-1b), interleukin 6 (IL-6), and tumor necrosis factor alpha (TNF-α), among others." (PMID 33961166, 2021). "Previous studies have investigated the pathogenesis of periodontitis and its association with the inflammatory cytokines IL-1β, IL-4, IL-6, IL-10, interferon-γ (IFN-γ), and TNF-α39." (PMID 34764408, 2021). "Recently a study wanted to analyze and identify the association among salivary interleukin-6 (IL-6) levels and periodontitis (PT) and to determine the significant trend of this association in PT patients." (PMID 34149840, 2021). "IL-6 increases the production of acute-phase proteins in the liver, and has also been linked to bone resorption in periodontitis." (PMID 34408814, 2021). "Periodontitis is associated with several host responses, including expression of IL-1β, IL-6, and TNF-α in response to oral bacteria." (PMID 34592963, 2021). "The most commonly identified cytokine by selbal, IL-6, was found in the original study to be significantly associated with severe periodontitis, while we found that IL-6 levels were predictive of pretreatment samples and samples that improved." (PMID 34079525, 2021). "The IL-6 is associated with chronic inflammation, and is considered to be a biomarker for chronic periodontitis." (PMID 35048045, 2021). "Another study reported an IL-6 gene polymorphism, which is considered as a susceptibility factor for chronic periodontitis in a Chinese population." (PMID 34835489, 2021). "Oral pathogens drive pathogenic Th17 differentiation in periodontitis via interleukin-6 (IL-6) and IL-23 signaling." (PMID 34869062, 2021). "Comprehensively, periodontitis predisposes transplant recipients to higher systemic inflammatory state, with an average of 2.20 pg/mL above the IL-6 levels." (PMID 32230707, 2020). "Periodontitis is also associated with higher serum levels of inflammatory biomarkers such as interleukin (IL)-6/17, prostaglandin, and C-reactive protein." (PMID 32698486, 2020). "Our results are similar to those in showed in previous animal and human studies, in which increased serum levels of IL-6 were associated with the presence of periodontitis." (PMID 31583485, 2020).
periodontitis (continued). "The salivary concentration of IL-6 significantly increased in obese individuals with high cumulative risk score for periodontitis." (PMID 33081038, 2020). "In the present animal study, experimental periodontitis was associated with increased serum levels of systemic inflammatory biomarkers such as IL-6, PTX3, and sTWEAK during 21 days of experiment." (PMID 31583485, 2020). "This study investigates the association between periodontitis and coronary artery disease, through the presence of PCR and IL-6 polymorphisms." (PMID 32215496, 2020). "Recently, periodontitis was found to be associated with high levels of IL-6, PTX3, and sTWEAK in patients with cerebral small vessel disease increasing almost 3 times the likelihood of having this type of AVD." (PMID 31583485, 2020). "During periodontitis, IL-6 has been associated with the detection of exFoxp3 Th17 cells, a population of Th17 cells that, at one point, expressed, but ultimately lost the Foxp3 expression." (PMID 33149125, 2020). "IL-6 is a pro-inflammatory cytokine usually increased in periodontitis patients, and it has been likewise associated with the augmented incidence of myocardial infarction and mortality." (PMID 33159128, 2020). "In these transplanted patients, there was moderate quality evidence that periodontitis is associated with higher IL-6 serum levels." (PMID 32230707, 2020). "In saliva, aMMP-8/MMP-8 is also among the best five biomarkers, and the combination of aMMP-8/MMP-8 and IL-6 seems the most promising salivary diagnostic marker for periodontitis." (PMID 31979091, 2020). "SOCS3 deficiency results in increased alveolar loss with high levels of IL-1β, IL-6, and IL-8 in periodontitis." (PMID 31304055, 2019). "Statins were shown to suppress inflammatory factors associated with periodontitis such as IL-6, TNF-α, IL-1β, as well as periodontal pathogens Pg and Aa." (PMID 31196047, 2019). "Another cross-sectional study demonstrated that the increased serum levels of TNF-α and IL-6 in patients with AD were significantly associated with periodontitis." (PMID 31366073, 2019). "AGEs, a major factor in DM complications, is thought to influence DM-associated periodontitis by regulating oxidative stress and IL-6, and ICAM-1 expression levels in HGFs." (PMID 31619000, 2019). "Both periodontitis and peri-implantitis have been proven to be associated with several host susceptible genes, such as interleukin-1, interleukin-6, tumor necrosis factor-alpha, and transforming growth factor beta." (PMID 31636864, 2019). "In periodontitis, NF-κB p65 can be significantly activated by P. gingivalis LPS, and its phosphorylation is closely associated with IL-6 production and periodontal damage." (PMID 31684930, 2019). "The increase in systemic markers of inflammation such as C-reactive protein, interleukin 6, and tumor necrosis factor-α in the plasma of periodontitis patients supports this association." (PMID 31195790, 2019). "As a result, we found that IL-10 AA genotypes were associated with chronic periodontitis and IL-10 AA genotype carriers showed lower IL-6/IL-10 levels in serum." (PMID 29489938, 2018). "This is indicative of the key association between chronic periodontitis and higher levels of visfatin, IL-6, and TNF-α." (PMID 30186882, 2018). "The most extensively studied polymorphism is of IL-6 gene especially in subjects with aggressive periodontitis." (PMID 29760828, 2018). "The same study discussed that IL-6 was associated with greater PD in cardiovascular patients suffering from chronic periodontitis and highlighted its role in inducing the synthesis of c-reactive proteins in cardiovascular patients." (PMID 30186882, 2018). "Rgps-mediated PAR2 activation enhanced the biosynthesis of prostaglandin E2, IFN-ɤ, IL-1β, and IL-6, which led to accelerated alveolar bone loss in experimentally-induced periodontitis in mice." (PMID 28589098, 2017).
periodontitis (continued). "We analyzed the effects of non-surgical perio-dontal therapy on the clinical parameters between SCP and NSCP to chronic periodontitis, according to the IL-6 -572 G/C, IL-10 -592 C/A polymorphisms as well as their combination." (PMID 28624837, 2017). "Studies have shown that other salivary inflammatory markers, including tumor necrosis factor- alpha, matrix metaloproteinases, interleukin-6, and interleukin-8, are associated with dental health and periodontitis." (PMID 28253297, 2017). "Both meta-analyses that aimed to clarify the association between IL-6 -572 G/C polymorphism and periodontal disease susceptibility revealed a significant increased risk of chronic periodontitis in patients with GG genotype." (PMID 28624837, 2017). "Meta-analyses have also confirmed a positive association between IL-6, IL-10 gene polymorphisms and chronic periodontitis." (PMID 28624837, 2017). "RA and periodontitis exhibit similar pathological features that are associated with the overproduction of pro-inflammatory cytokines such as interleukin-6 (IL-6) and tumor necrosis factor-alpha (TNF-α)." (PMID 27111223, 2016). "IL-8 and IL-6 are directly or indirectly involved in osteoclastogenesis, and are responsible for the alveolar bone loss in periodontitis." (PMID 25058444, 2014). "The aim of this study was to investigate the association between the IL6 c.-174G>C polymorphism and periodontitis in individuals from Vitória da Conquista, Bahia, Brazil." (PMID 25548674, 2014). "In order to verify the association with periodontitis, the frequencies of each genotype for the IL6 c.-174G>C polymorphism were compared in case and control groups." (PMID 25548674, 2014). "In the present study, a positive association was found between IL6 c.-174G>C gene polymorphism and periodontitis, considering the frequency distribution of GG, GC, and CC genotypes among the case and control groups (P = 0.038)." (PMID 25548674, 2014). "The data in the literature regarding the quantification of IL-6 in salivary fluid, the polymorphism c.-174G>C, and periodontitis are scarce." (PMID 25548674, 2014). "Our findings showed that the IL-6 increased levels in the case group indicate that the higher production of this cytokine is associated with periodontitis and its inflammation response." (PMID 25548674, 2014). "IL-6 is also one of the cytokines found in the GCF of patients with refractory periodontitis who are undergoing active bone loss." (PMID 24151615, 2013). "Our findings are in fact at variance with other investigations showing that gene variations of INF-γ, IL-1β and IL-6 were associated with periodontitis." (PMID 24274085, 2013). "The low-grade inflammation associated with chronic periodontitis is characterized by increased levels of circulating pro-inflammatory cytokines (IL-1, IL-6, tumor necrosis factor α) and C-reactive protein." (PMID 23526947, 2013). "Periodontitis patients carrying one or two copies of the rare allele in the IL-6 -174 polymorphism displayed significantly higher serum IL-6 and C-reactive protein concentrations." (PMID 23046796, 2012). "Periodontitis has also been associated with elevations in circulating levels of IL-6 and C-reactive protein (CRP)." (PMID 23009606, 2012). "Recent studies have shown an association between high levels of CRP and IL-6 and periodontitis, an association that decreases after periodontal treatment." (PMID 23009606, 2012). "Similarly, the ROC analysis results in our study are noteworthy: IL-6 demonstrated exceptionally high diagnostic performance for periodontitis, with a sensitivity of 93.9% and a specificity of 97.0%, indicating near-perfect accuracy." (PMID 41007333, 2025). "Moreover, a lot of studies have demonstrated that nucleotide polymorphisms of IL-6 are correlated with the progression of periodontitis." (PMID 41300760, 2025).